GSTM1 (glutathione S-transferase mu 1)
Diseases named in the same sentence as GSTM1 in open-access papers (continued):
Sharing a sentence is not in itself a finding about the gene and the disease.
bladder cancer (continued). "In a large case–control study, we reported that 63% of bladder cancer cases and 47% of controls harbored the GSTM1-null genotype, leading to an OR = 1.7 (95%CI 1.4 – 2.0)." (PMID 22817656, 2012). "It is well established that a deletion variant of the detoxifying phase II metabolizing enzyme glutathione S-transferase M1 (GSTM1), in addition to N-acetyltransferase 2 (NAT2) slow acetylation are associated with increased urinary bladder cancer risk." (PMID 23284801, 2012). "The evidence generally supports the modulating effect of GSTM1 and GSTT1 polymorphisms on cancers closely-related to chemical exposure, including bladder cancer." (PMID 21798077, 2011). "The associations with bladder cancer risk for NAT2 slow versus rapid/intermediate acetylator and GSTM1 null versus present within each THM stratum were variable and consistent with the overall elevated main effects for these genes." (PMID 20675267, 2010). "Mutations in DNA repair genes (XRCC3) and variants in genes coding for xenobiotic-transforming enzymes (NAT2, GSTM1, GSTP1 and NQO1) have been shown to modify the susceptibility to bladder cancer." (PMID 19755987, 2009). "We evaluated interactions between the VEGF SNPs significantly associated with bladder cancer risk and other determinants of risk (i.e., age, gender, smoking status, family history of cancer in at least one first-degree relative, and NAT2 and GSTM1 genotypes)." (PMID 17319747, 2007). "In summary, these prospective results are consistent with previous literature supporting associations between bladder cancer and the NAT2 slow acetylation and the GSTM1 null genotypes." (PMID 17026750, 2006). "We did not observe any statistically significant effect modification by cigarette smoking status for the GSTM1 and the GSTT1 null genotypes and bladder cancer risk (p for interaction > 0.30)." (PMID 17026750, 2006). "There is strong evidence of colocalization between GSTM1 and bladder cancer." (PMID 39898788, 2025). "The associations of GSTM4 and KLC1 but not GSTM1 with bladder cancer risk were replicated (FDR < 0.1) using the corresponding cis-pQTLs from the Fenland study." (PMID 39898788, 2025). "Moreover, genes such as NAT2, TP63, GSTM1, MYC, TACC3‐FGFR3, PSCA, CLPTM1L‐TERT, APOBEC3A‐CBX6, UGT1A, and CCNE1 get mutated in bladder cancer." (PMID 40755497, 2025). "In current study, we examined whether polymorphisms of GSTM1 and NAT2 changed or accounted for the increased risk of bladder cancer independently and in combination with tobacco use among the Mongolian population." (PMID 34452561, 2021). "On the other hand, data validity assessment demonstrated a 4.4-fold elevated risk of bladder cancer in smokers with the GSTM1-null genotype as opposed to GSTM1-active nonsmokers." (PMID 31275451, 2019). "This study focuses on the impact of GSTM1 null genotype on bladder cancer patients’ outcome." (PMID 31646988, 2019). "Together, our data showed that GSTM1 gene deletion either alone or in combination with HER2 may serve as markers for bladder cancer prognosis." (PMID 31646988, 2019). "The null genotype of both GSTM1 and GSTT1 is also associated with increased risk of bladder cancer." (PMID 27911277, 2017). "This discrepancy could be explained by different effects of the GSTM1 and GSTT1 polymorphisms on bladder cancer susceptibility in different ethnic groups." (PMID 27911277, 2017). "Subgroup analyses indicated that the GSTM1-null genotype was associated with increased risk of bladder cancer in Caucasians and Asians, while the GSTT1-null genotype was associated with increased risk of bladder cancer in Caucasians." (PMID 27911277, 2017). "After stratification by smoking status, the GSTM1 deletion was associated with an increased bladder cancer risk in both smokers and nonsmokers." (PMID 27911277, 2017). "Second, the GSTM1 gene is always deleted in human bladder cancer cells." (PMID 27404495, 2016).
bladder cancer (continued). "An increased frequency of GSTM1 and GSTT1 null genotypes has been associated with several types of malignancies, including stomach cancer, lung cancer, pituitary adenomas, bladder cancer, prostate cancer, cervical cancer, and acute leukemia." (PMID 24194954, 2013). "Therefore, we determined the most influential genetic variants (rs1014971, rs11892031, rs1495741, rs710521, rs8102137, rs9642880, and GSTM1) in 1,595 bladder cancer cases and 1,760 controls." (PMID 23284801, 2012). "It is noteworthy the fact that, using CNV calls derived from Illumina 1 M platform, GSTM1 would have never been associated with bladder cancer." (PMID 22817656, 2012). "Our data indicated that the strength of the association of bladder cancer with GSTM1 null is not affected by exposure to DBPs." (PMID 20675267, 2010). "They found a significant interaction between NAT2 and the number of cigarettes per day in bladder cancer risk by case-only analysis, while the risk estimate for GSTM1 was not modified by ethnicity nor by smoking intensity." (PMID 22275976, 2008). "In summary, our data support the prior evidence that the GSTM1 null genotype and the NAT2 slow acetylation genotype may affect an individual's bladder cancer risk." (PMID 17026750, 2006). "The association between GSTT1 polymorphism and bladder cancer risk remained similar after stratification by smoking status (p for interaction = 0.69), and no significant gene-gene interactions with GSTM1 and GSTT1 were detected (p for interaction = 0.22)." (PMID 17026750, 2006). "Given their biological role, polymorphisms within the GSTT1, GSTM1, NAT1, and NAT2 genes may be important in determining an individual's susceptibility to bladder cancer." (PMID 17026750, 2006). "Because the metabolism of tobacco-related carcinogens may be influenced by the activity of GSTs, polymorphisms in GSTM1 and GSTT1 may modify the risk of bladder cancer associated with these carcinogens." (PMID 17026750, 2006). "Previous studies correlated the absence of the GSTM1 protein with an increased risk of developing some cancers, especially lung or bladder cancers, in heavy smokers." (PMID 9888479, 1999). "Moreover, glutathione-S-transferase M1 (GSTM1), which binds to reduced glutathione to catalyze the detoxification of foreign substances, is also considered a metabolic target for gender differences in bladder cancer incidence rates." (PMID 38283839, 2023). "GSTM1 deletion was associated with increased bladder cancer risk in both smokers and nonsmokers." (PMID 27911277, 2017). "Non-smokers with the GSTM1/GSTT1 double-null genotype had an increased bladder cancer risk." (PMID 27911277, 2017). "Non-smokers with GSTM1/GSTT1 double-null genotype had an elevated bladder cancer risk." (PMID 27911277, 2017). "Only one study reported the relationship between GSTM1/ GSTT1 double-null genotype and the risk of bladder cancer stratified by smoking status; this study showed that non-smokers with GSTM1/ GSTT1 double-null genotype had an elevated bladder cancer risk (OR=2.66, 95%CI: 1.22–5.81)." (PMID 27911277, 2017). "Although in meta-analysis the effect of GSTM1 null genotype on BC risk was increased by smoking habit, the joint effect of GSTM1 null genotype was not greater among smokers, never and former smokers in the present study, as well as in New England bladder cancer study." (PMID 24919441, 2014). "Additionally, female smokers were shown to have a higher risk of bladder cancer when their blood samples had the GSTM1 deletion genotype, but not in non-smokers, possibly due to females with the GSTM1 null genotype being unable to metabolize carcinogens in cigarette smoke." (PMID 38283839, 2023). "Genotyping of GSTM1 and GSTP1 in bladder cancer patients was assessed using polymerase chain reaction followed by DNA sequencing." (PMID 31646988, 2019). "It has also been estimated that a slow acetylation phenotype in both GSTM1 and NAT2 may account for up to 31% of bladder cancer case patients." (PMID 39898788, 2025).
bladder cancer (continued). "The frequency of GSTM1 null genotype was higher in controls (71.67%) than in bladder cancer patients (58.33%), but without statistical significance (OR=0.55; 95% CI=0.26-1.18), (p=0.128)." (PMID 34452561, 2021). "The frequency of GSTM1 null genotype was higher in controls (71.67%) than in bladder cancer patients (58.33%) without statistical significance (OR=0.5534; 95% CI=0.2586-1.1843), (p=0.128)." (PMID 34452561, 2021). "In our study, the GSTM1 null genotype was more common in healthy controls (71.67%) than in bladder cancer patients (58.33%) without statistical significance (OR=0.55; 95% CI=0.26-1.18), (p=0.128)." (PMID 34452561, 2021). "The frequency of GSTM1 null genotype in females was slightly higher (73.09%) in control group than bladder cancer group, but there was no statistical significance (OR=0.27; 95% CI=0.07-1.09), (p=0.065)." (PMID 34452561, 2021). "Therefore, further analyses using larger sample size are needed to investigate the functional significance of combined GSTM1 deletion and HER2 on bladder cancer prognosis." (PMID 31646988, 2019). "The exact mechanism of the influence of GSTM1 and HER2 on bladder cancer is yet to be elucidated." (PMID 31646988, 2019). "In summary, down-regulation of the GSTM1 gene and the p21 protein might act as biomarkers in nitrosamines-induced bladder carcinogenesis in mice, while GSTM1 null and GSTM5 hypermethylation might act as bladder cancer biomarkers in humans." (PMID 27404495, 2016). "In the well-characterized region of GSTM1, we found that PennCNV did not detect any deletion in a large sample of cases with bladder cancer and controls where homozygous deletion was known to have a frequency of 50% using Taqman and MLPA technologies." (PMID 22817656, 2012). "We compared the distributions of the GSTM1, GSTT1, NAT1, and NAT2 genotypes between incident and prevalent bladder cancer cases in men and women separately to determine whether the variant alleles were associated with survival." (PMID 17026750, 2006). "Furthermore, combined GSTM1 deletion and amplified HER2 gene might be considered as the worse prognostic genotype combination in bladder cancer." (PMID 31646988, 2019). "Unlike mouse GSTM1, the human GSTM1 gene tends to be deleted in bladder cancers." (PMID 27404495, 2016). "The fact that the association between GSTM1 CNV and bladder cancer can be detected with LRR values without applying a calling CNV confirms the utility of this measure as a complementary screening strategy to test for association at the genome-wide level, as already suggested." (PMID 22817656, 2012).
asthma (42 papers, 2007 to 2024). "Subsequently, similar studies have also identified significant interactions between household air pollution, GSTM1 null genotypes and asthma risk." (PMID 36250015, 2022). "In a recent meta-analysis of 41 case-control studies, the pooled results showed a significant association of asthma with both the GSTM1 (OR = 1.21) and GSTT1 (OR = 1.61) genotypes." (PMID 35186174, 2022). "Meanwhile, there were five different genes that were consistently downregulated in ciliated cells following Tet1 loss and/or HDM treatment, including the asthma-associated genes Gstp1, Gstm1, and Gpx2." (PMID 35627266, 2022). "The genotype combinations GSTT1 ∗ GSTP1 rs762803 and GSTM1 ∗ EPHX1 rs2854450 were also associated with diisocyanate-induced asthma." (PMID 35186174, 2022). "A study of workers with SIC-confirmed diisocyanate-induced asthma (n = 95) revealed that the GSTM1 null and GSTP1 rs762803 genotypes were risk variants." (PMID 35186174, 2022). "Influence of GSTM1 polymorphisms on the relationship between household environmental exposures and asthma and lung function." (PMID 36250015, 2022). "Two systematic reviews have been conducted on the associations between GSTM1/T1/P1 genotypes and asthma." (PMID 36250015, 2022). "Isocyanate-induced asthma is associated with the GSTM1 null genotype in Caucasians, and the GSTP1 Val/Val genotype is less frequent in asthmatics exposed to TDI for 10 or more years." (PMID 35186174, 2022). "The authors concluded that the findings of previous studies, positive associations between GSTT1 null and asthma and GSTM1 null and asthma severity, were false-positive findings." (PMID 32380770, 2020). "We are the first to show the higher CG methylation content of the LMO2 or IL10 is correlated to prenatal exposure of PTS, and the combination of LMO2_E148 (≧28.5%), IL10_P325 (≧38.5%), and GSTM1_P266 (≧41.5%) reveals the highest risk to childhood asthma." (PMID 31214241, 2019). "Recent studies have also shown that Nrf2-driven GST is a possible marker for asthma susceptibility in humans: the homozygous GSTM1-null genotype increases the risk for asthma, but homozygous GSTP1 expression can protect against asthma." (PMID 30728889, 2019). "In a meta-analysis, increased risk for asthma was found in the presence of the GSTM1 and GSTT1 low activity genotypes, the risk varying depending on ethnicity." (PMID 31649932, 2019). "Prenatal tobacco exposure has a significant impact on asthma development and DNA methylation dependent on the polymorphism of the redox gene, GSTM1." (PMID 31214241, 2019). "The null genotype of GSTM1 has been suggested to be associated with the risk of a number of diseases, including alcoholic liver disease and asthma." (PMID 25742618, 2015). "Another study showed that maternal use of acetaminophen in late pregnancy increased the risk of asthma or wheezing in children when the maternal or child's GSTM1 genotype was positive." (PMID 25328891, 2014). "Most previous studies have reported that the GSTM1 null genotype significantly increases the risk for asthma development, although some studies found this risk to be insignificant." (PMID 25328891, 2014). "This study demonstrates that the GSTM1 null genotype presents a protective effect against asthma development in girls, but the risk of asthma development increases significantly under prenatal TSE." (PMID 25328891, 2014). "Further analysis showed that prenatal TSE significantly increased the risk of childhood asthma in girls with null-GSTM1." (PMID 25328891, 2014). "Some studies have revealed that the GSTM1 null genotype significantly increases the risk of asthma in children and adults." (PMID 25328891, 2014). "Individuals with the GSTM1 null genotype completely lack the GSTM1 enzyme activity and their susceptibility to asthma and lower lung function is increased." (PMID 22867088, 2012).
asthma (continued). "The loss of the GSTM1 gene (GSTM1 null) was shown to be associated with a 1.89-fold increased risk to develop isocyanate-induced asthma." (PMID 22016709, 2011). "A recent meta-analysis of GST genes and asthma phenotypes reported that GSTM1 and GSTT1 showed increased asthma risk associated with the null genotype but that heterogeneity across studies and publication bias was a major limitation." (PMID 21320344, 2011). "Statistically significant associations with asthma were observed for SNPs in GSTM1, MS4A2, and GSTP1 genes, after correction for multiple testing." (PMID 21320344, 2011). "Statistically significant associations were only observed for the asthma phenotype, for SNPs in GSTM1, MS4A2, and GSTP1, after correction for multiple testing." (PMID 21320344, 2011). "We have previously reported that GSTM1 is associated with asthma risk in children exposed to tobacco smoke." (PMID 18335111, 2008). "Interaction between GSTP1 and GSTM1 has been reported for xenobiotic enhancement of allergic responses and on childhood asthma risk." (PMID 18335111, 2008). "We found that GSTM1 null genotype was significantlyassociated with increased risk of asthma (P = .002)." (PMID 17497028, 2007). "Thus, of the GST family members, GSTM1 appears to be most frequently associated with diisocyanate-induced asthma." (PMID 35186174, 2022). "One meta-analysis showed that the GSTM1 null genotype may be associated with an increased risk of asthma (pooled OR 1.28; 95% CI 1.09–1.52), with large between-study heterogeneity." (PMID 25328891, 2014). "Additionally, we found that prenatal TSE increases the risk of childhood asthma in individuals with the GSTM1 null genotype, which supports the findings of other studies." (PMID 25328891, 2014). "Furthermore, among children without prenatal TSE, females with the GSTM1 null genotype had a significantly lower risk of developing childhood asthma compared with females with positive GSTM1 (9.4% versus 19.3%, P = 0.037, OR: 0.436, 95% CI: 0.197–0.966)." (PMID 25328891, 2014). "Furthermore, among the children without prenatal TSE, girls with null-GSTM1 had a significantly lower risk of developing childhood asthma and a lower total IgE level at 6 years of age than those with positive GSTM1." (PMID 25328891, 2014). "Piirilä and co-workers, found an increased risk of diisocyanate-asthma among GSTM1*O subjects." (PMID 18447907, 2008). "Studies focusing on the impact of ozone exposure have corroborated that polymorphisms in oxidative stress genes, such as NQO1, GSTM1, and GSTP1, can precipitate respiratory symptoms and elevate the risk of asthma development." (PMID 39316602, 2024). "A meta-analysis of 26 case–control studies involving 3000 participants linked deletions in GSTM1 and GSTT1 genes to an increased risk of asthma." (PMID 39594473, 2024). "One study investigated a dose-response relationship between GSTM1, GSTP1 genotypes, another respiratory inflammatory biomarker, Clara Cell secretory protein-16, (CC16) and asthma risk." (PMID 36250015, 2022). "A recent meta-analysis demonstrated that GSTM1 and GSTT1 null genotypes are associated with an increased risk of asthma." (PMID 35186174, 2022). "GSTM1 (OR 10.39, 95% CI 4.42, 24.46) and GSTT1 (OR 19.15, 95%CI 7.28, 50.41) null genotypes were associated with increased risk of asthma." (PMID 36250015, 2022). "Several asthma-related genes were identified: detoxification enzymes (Cyp2a5, Gsto1, Gstp1, Gstm1, and Aldh1a1) were downregulated while Hmgb1 (alarmin) was upregulated." (PMID 35627266, 2022). "Overall, there was less evidence for an interaction in relation to asthma outcomes (compared to GSTM1)." (PMID 36250015, 2022). "We found that the GSTM1 null genotype was more frequent in the TDI-PA than in the TDI-NA group and was associated with a three-fold increased risk of developing asthma after TDI exposure." (PMID 35186174, 2022).